CDCP1 (CUB domain containing protein 1)
Diseases named in the same sentence as CDCP1 in open-access papers (continued):
Sharing a sentence is not in itself a finding about the gene and the disease.
cancer (continued). "So, we postulated that differential glycosylation, perhaps via altered proteolysis, regulates CDCP1 expression and its role in cancer progression." (PMID 26497208, 2015). "The use of specific anti-CDCP1 antibodies has been proposed as a therapeutic strategy for targeting cancer cells overexpressing CDCP1." (PMID 25876044, 2015). "Specifically, CDCP1 localization to membrane lipid rafts was shown to be a prerequisite to invadopodia-mediated cell invasion, and cell migration in an ovarion cancer model required EGF-induced relocalization of CDCP1 to the cell surface." (PMID 26497208, 2015). "CDCP1 is a type I transmembrane protein with broad expression in normal tissues, but with an established role in cancer progression (reviewed by Uekita and Sakai–)." (PMID 26227951, 2015). "A number of recent studies have assigned a potentially important role for the cell-surface protein CDCP1 in invasion and metastasis of a several types of human cancer cells." (PMID 25301083, 2014). "Consistent with this, a number of studies have shown that CDCP1 modulates adhesion of cancer cell lines to an extracellular matrix (ECM)." (PMID 25301083, 2014). "CDCP1 has also been shown to affect cell migration and adhesion in vitro as well increasing metastasis of cancer cell lines in certain in vivo model systems." (PMID 25301083, 2014). "Although CDCP1 has been studied in various cancers, its role in PDAC remains largely unexplored." (PMID 41488282, 2026). "Similarly, a promising area of investigation in SETD2-mutated cancer is into immune checkpoint expression, such as HAVCR2, CTLA-4, or TIGIT or biomarkers such as CDCP1 and AXL." (PMID 41228333, 2025). "CDCP1 promotes cancer cell survival, growth, and metastasis." (PMID 38683990, 2024). "Given that CDCP1 regulates several signaling pathways for tumor malignancy, it could be a potential target for cancer treatment." (PMID 37013960, 2023). "Moreover, CDCP1 is overexpressed in various cancers, including colon, kidney, lung, breast, pancreas, liver, ovary, and prostate cancers." (PMID 36862682, 2023). "The role of CD318 (CDCP1) in cancer has been extensively explored." (PMID 36275816, 2022). "Dysregulated CDCP1 expression is known to affect progression in several cancers." (PMID 35054034, 2022). "We first compiled CDCP1 mRNA expression profiles from datasets from the Pan-Cancer Analysis of Whole Genomes (PCAWG) Consortium, the Therapeutically Applicable Research to Generate Effective Treatments (TARGET) initiative and the Genotype Tissue Expression (GTEx) project 20-22." (PMID 36276654, 2022). "Similar results were seen in the reverse assay format where an equal amount of unlabelled 10D7 halved the accumulation of fluorophore-labelled ch10D7-550 on the surface of cancer cells (second top) supporting that ch10D7 binds with similar affinity to CDCP1 as 10D7." (PMID 36276654, 2022). "A growing number of studies uncover the multiple roles of CDCP1 in cancers." (PMID 36090897, 2022). "We also examine CDCP1 expression in a broad range of cancers and 34 normal human tissues to provide insight into the proportion of patients who could benefit from CDCP1 targeted theranostics and ADCs." (PMID 36276654, 2022). "Moreover, the tumor initiating role of CDCP1 has been identified in GC as evidenced by its function in accelerating migratory and invasive potential of cancer cells." (PMID 33882457, 2021). "Further analyses of the functions of the CDCP1-Src-Met-STAT3 pathway in a wide range of cancer cells may reveal potentially new therapeutic targets for the treatment of some malignant cancers." (PMID 33574034, 2021). "Indeed, we found that overexpression of CDCP1 in MDCK cysts induced the expression of cytokeratin 14, a promising marker of collective invasion of cancer cells, suggesting a potential role of up-regulation of the CDCP1-Src axis in this process." (PMID 33574034, 2021). "CDCP-1 has been a target of interest for targeted-imaging as well as therapy in various cancers." (PMID 34885196, 2021).
cancer (continued). "Based on the growing literature reporting the functional roles of CDCP1 in resistance to therapies in various cancer types 11, 16, 17, 48, 10D7-based imaging may also be useful in measuring responsiveness to targeted therapies." (PMID 32104500, 2020). "Upregulation of CDCP1 expression in response to transformation by RAS30, an oncogene somatically mutated in more than 90% of PDAC tumors 31, is also suggestive of a functional role for CDCP1 in this cancer." (PMID 32226543, 2020). "CDCP1 expression and patient survival are inversely associated, which is suggestive that CDCP1 is functionally involved in progression of PDAC and represent an interesting target to develop anti-cancer agents for PDAC." (PMID 32226543, 2020). "CDCP1 increases the migration and invasiveness of cancer cells and anchorage-independent cell survival through its interaction with important signalling pathways in tumor aggressiveness, such as Akt, PKCδ, Src, and Extracellular signal-regulated kinases 1–2 (ERK1/2)." (PMID 29792166, 2018). "However, we believe that our collective observations provide motivation for the further exploration of CDCP1 an antibody target for RAS mutant cancers." (PMID 29359686, 2018). "CDCP1 is a cleavable transmembrane protein that is overexpressed in several types of cancer cells." (PMID 29792166, 2018). "Due to the significance of these proteases in cancer progression and metastasis, we investigated the ability of the matriptase inhibitor kempopeptins C to target the downstream cellular substrates Dsg-2 and CDCP1." (PMID 28926939, 2017). "This may in turn account for the relationship between CDCP1 or EGFR expression in cancer and increased invasiveness, elevated cancer dissemination, and poor patient outcome." (PMID 27495374, 2016). "In summary, CDCP1 has important and targetable roles in cancer." (PMID 26973855, 2016). "Cub Domain Containing Protein 1 (CDCP1/gp140/Trask) is a transmembrane glycoprotein that facilitates integrin-dependent migration and invasion and whose elevated expression in primary tumors correlates with metastasis in several cancers." (PMID 25730905, 2015). "In cancer cells, both forms of CDCP1 are tyrosine phosphorylated in the event of cell adhesion." (PMID 26497208, 2015). "However, some uncertainty exists on the link between CDCP1 expression and tumour prognosis, since contradictory effects have been observed in different cancer types." (PMID 26227951, 2015). "CDCP1 has been shown to play a role in cell motility and adhesion of certain cancer cell lines." (PMID 25301083, 2014). "CDCP1 gene regulation has been investigated in various cancer cell lines." (PMID 22390300, 2012). "Therefore, blocking CDCP1 function is a promising approach for cancer treatment." (PMID 38683990, 2024). "In addition, as the ECD of CDCP1 is known to be proteolytically processed 31, 42 it will be important to understand how proteolysis impacts the effectiveness of CDCP1-targeted agents for cancer detection and treatment." (PMID 32104500, 2020). "Due to the significance of these proteases in cancer progression and metastasis, as well as their functional redundancy with respect to targeting overlapping substrates, we examined the effect of kempopeptin C on the downstream cellular substrates of matriptase: CDCP1 and desmoglein-2 (Dsg-2)." (PMID 28926939, 2017). "Promising data from preclinical studies suggest that CDCP1 targeted agents, including therapeutic antibodies, could be useful in the treatment of cancer patients selected on the basis of activation of CDCP1 and its signaling partners including EGFR, HER2, Met and Src." (PMID 26973855, 2016). "To determine whether CDCP1 has prometastatic activity, as suggested for certain human cancer histotypes, we analyzed the in vitro migration, invasion, and proliferation of 2 TNBC cell lines (BT-549 and MDA-MB-231) that highly express CDCP1, migrate, and invade, after silencing CDCP1." (PMID 27626701, 2016).
cancer (continued). "Conditioned by CDCP1-high SW480 or HCT116 cells, CAFs displayed a protumor phenotype with upregulation of α-SMA, FAP, PDGFRβ, and S100A4, indicating that cancer-cell CDCP1 promotes fibroblast activation." (PMID 41301830, 2025). "As an oncogene, the CUB domain-containing protein 1 (CDCP1) has emerged as a potential biomarker and therapeutic target in various cancers." (PMID 37284313, 2023). "Conversely, MTA2, DDX46, CDCP1, and CELF1, which have been reported to play a role in at least one of these processes in CRC, are known to promote cancer." (PMID 37510319, 2023). "CD318 (CDCP1) is found overexpressed by epithelial and myeloid cancer cells, where it correlates with cancer progression and metastasis initiation." (PMID 38139340, 2023). "PKCδ can be phosphorylated by CDCP1/SFK complex through the interaction of the C2 domain of PKCδ to enhance anoikis resistance and migration/invasion abilities of cancer cells." (PMID 36862682, 2023). "Not only does CD318 (CDCP1) play an important role in the initiation of metastasis, but it also mediates cancer progression by altering cancer cell growth." (PMID 36275816, 2022). "Given CDCP1 is highly expressed in RAS-driven cancers, targeting a proteolytic neoepitope on CDCP1 is a pan-cancer approach to control RAS-driven cancers." (PMID 36090897, 2022). "CUB-domain containing protein 1 (CDCP1) is a transmembrane protein acting as an effector of SRC family kinases, which play an oncogenic role in multiple human cancers." (PMID 36090897, 2022). "Cub domain-containing protein 1 (CDCP1), also known as CD318, is a transmembrane glycoprotein expressed by fibroblasts and the epithelium of normal and cancer cells." (PMID 36275816, 2022). "A recombinant human/mouse chimeric anti-CDCP1 antibody (ch10D7) was labelled with 89Zirconium or monomethyl auristatin E (MMAE) and tested in multiple pre-clinical cancer models including 36 cancer cell lines and three mouse xenograft models." (PMID 36276654, 2022). "The same analysis conducted on TMA7, SPCS2, CDCP1, NT5C3A and SRP54 revealed a homogeneous expression in the majority of 33 TCGA histotypes of cancer." (PMID 33925480, 2021). "Our in vitro findings presented here suggest that CDCP1-mediated activation of the Src-STAT3 pathway contributes to malignant progression by inducing invasion-like and growth-promoting phenotypes, even in cancer cells." (PMID 33574034, 2021). "We have previously shown that antibody-based CDCP1 directed agents are effective for PET-CT imaging and treatment of preclinical models of ovarian and pancreatic cancer." (PMID 34621145, 2021). "CD318 (CDCP1, TRASK, SIMA135, or gp140) is a cell surface glycoprotein that is widely expressed by cancer cells, and its degree of expression correlates with cancer aggressiveness and metastatic potential." (PMID 33497367, 2021). "Nevertheless, extrapolating from our data, it is possible that CDCP1-targeted agents will display efficacy for detection and treatment of EOC and other CDCP1 expressing cancers." (PMID 32104500, 2020). "An important issue for the effectiveness of CDCP1-trageted agents for imaging and treatment of EOC and other cancers will be the proportion of malignant cells that express this receptor on the cell surface." (PMID 32104500, 2020). "For instance, in cancer cells, coactivation of Axl with EGFR or CUB domain–containing protein-1 (CDCP1) has been shown to enhance cancer cell survival and their invasiveness." (PMID 32970632, 2020). "Here, we applied our novel antibodies to CDCP1 to begin to validate its potential as a therapeutic target and as a biomarker in RAS-driven cancers dependent on MAPK signaling." (PMID 29359686, 2018). "We show that antibodies targeting CDCP1, a protein common to our proteomics and CRISPRi datasets, can be leveraged to deliver cytotoxic and immunotherapeutic payloads to RAS-transformed cancer cells and report for RAS signaling status in vivo." (PMID 29359686, 2018).
cancer (continued). "CD147 and CDCP1 were found significantly upregulated on the MCF10A-KRasG12V surface by LC-MS and were depicted in the two top IPA® networks (cell motility and cancer)." (PMID 27894102, 2016). "CUB domain-containing protein 1 (CDCP1), also known as gp140, SIMA135, and TRASK, is a type I-transmembrane glycoprotein that acts as a receptor tyrosine kinase to relay oncogenic signals to cancer progression." (PMID 40892739, 2025). "Additionally, we investigated CUB domain-containing protein 1 (CDCP1), which is highly overexpressed in RAS-driven cancers and undergoes ectodomain cleavage by extracellular proteases on cancer cells but not healthy cells." (PMID 40661577, 2025). "We next examined CDCP1, a protein overexpressedin RAS-driven cancers.The cleavage-specific antibody CL03 has previously been shown to localizeto tumors and exhibit antitumor activity with improved safety profiles, but it demonstrated limited internalization and inefficientdegradation of cCDCP1." (PMID 41091621, 2025). "The combination of CDCP1 and ITGA6 proteins may differentiate between OVCA and non-cancer groups with a higher AUC value (0.9653) than CDCP1 alone." (PMID 37469398, 2023). "Cell surface CDCP1 levels were largely independent of the cancer of origin although highest levels were apparent in five of the seven PDAC lines (purple)." (PMID 36276654, 2022). "However, CDCP1’s requirement for HGF-induced invasion and metastasis of human cancer cells was undetermined." (PMID 35085554, 2022). "cancer and PDAC (88.6%) tumors analyzed in this study exhibited CDCP1 immunohistochemical signal well above levels seen by us in 34 normal tissues, suggesting that these patients would most likely benefit from a CDCP1-targeted therapy." (PMID 36276654, 2022). "The delay in achieving adequate tumor-to-background signal after agent administration may negatively impact clinical implementation of an antibody-based CDCP1-directed PET imaging agent for CRC and other cancers." (PMID 34621145, 2021). "Expression of the cell surface protein CDCP1 is increased in CRC, and here we sought to assess whether it is a suitable molecular imaging target for the detection of this cancer." (PMID 34621145, 2021). "The current findings suggest a mechanism whereby CDCP1, EGFR, and Src cooperate to induce cancer aggressiveness and dissemination, and may provide a rationale for therapeutic targeting of these proteins in combination." (PMID 27495374, 2016). "CDCP1 likely contributes to metastasis, in part, by allowing cancer cells to survive and metastasize in the absence of attachment." (PMID 27495374, 2016). "CUB domain-containing protein-1 (CDCP1, also termed CD318, SIMA135 and Trask) is an 836 amino acid type I integral membrane glycoprotein that may play a role in cancer metastasis." (PMID 25301083, 2014). "Reduction of CDCP1 expression in SW480 cells by RNA interference resulted in decreased cell motility, a finding consistent with previous reports on the effect of CDCP1 on cancer cell motility." (PMID 25301083, 2014). "In addition, we have collected ascites and serum samples from women with OVCA and women without cancer, but the expression of CDCP1 is substantially different." (PMID 37469398, 2023). "Previous studies have demonstrated the utility of mouse monoclonal 10D7 antibody that binds to the CDCP1 amino terminal, for delivery of Zirconium-89 (89Zr) for PET-CT-based detection, and cytotoxins for treatment of preclinical models of ovarian and pancreatic cancer." (PMID 34621145, 2021). "Although examination of CDCP1 expression in frozen prostate tissues by immunofluorescence microscopy revealed significant differences in subcelluar distribution between cancer and adjacent normal, these results were not recapitulated in our survey of FFPE tissue." (PMID 26497208, 2015).
cancer (continued). "Importantly, studies carried out with a new class of anti-cancer agents (i.e., Disulfide bond Disrupting Agents [DDAs]), which target epidermal growth factor receptor (EGFR) and its family members HER2 and HER3, show that DDAs disrupt CDCP1 ternary signaling complexes." (PMID 27495374, 2016). "HGF makes the cancer cells independent of EGFR signaling and enables EGFR to interact with other proteins such as CUB domain-containing protein-1 (CDCP1), EphA2 and AXL, forming a c-Met (HGFR)-EGFR cross-talk that can't be inhibited by EGFR TKI treatment." (PMID 26405162, 2015). "Since CDCP1 knockdown did not affect MET mRNA expression, it is suggested that CDCP1 functionally interacts with MET and may contribute to the regulation of stability and/or turnover rate of MET protein in these cancer cells." (PMID 35085554, 2022). "In these cancers targeting CDCP1 with an ADC may not be appropriate due to unintended effects on normal epithelium, but labelled anti-CDCP1 antibodies may be of greater use as imaging agents to detect metastases, highlighting the potential of this antibody as a versatile molecular tool for cancer." (PMID 32104500, 2020). "Suppression of CDCP1 cleavage by TA may be preferable to that induced by TGFβ and glucocorticoids since these agents block Plasminogen activation by upregulating Plasminogen Activator Inhibitor-1 (PAI-1) and activate transcriptional programs that may not be beneficial in the cancer setting." (PMID 35095503, 2021).